SRC (SRC proto-oncogene, non-receptor tyrosine kinase)
Diseases named in the same sentence as SRC in open-access papers (continued):
Sharing a sentence is not in itself a finding about the gene and the disease.
cholangiocarcinoma (3 papers, 2016 to 2025). A carcinoma that arises from the intrahepatic biliary tree (intrahepatic cholangiocarcinoma) or from the junction, or adjacent to the junction, of the right and left hepatic ducts (hilar cholangiocarcinoma). "Collectively, these findings highlight tiliacorinine’s strong binding affinities to pivotal cholangiocarcinoma-related targets, including MTOR, SRC, MMP9, and MAPK1, underscoring its potential as a promising multi-target therapeutic candidate." (PMID 41300430, 2025).
cyst (3 papers, 2020 to 2024). A sac-like closed membranous structure that may be empty or contain fluid or amorphous material. "In summary, we show increased activation of SRC and STAT3 in cyst‐lining epithelia of ARPKD kidneys." (PMID 33112055, 2020). "We show that the C‐term of human FC can regulate SRC‐activation and that SRC and STAT3‐activation can be observed in ARPKD cyst‐lining epithelial cells." (PMID 33112055, 2020). "Moreover, tesevatinib, an inhibitor of EGFR, HER2, c-SRC, and VEGFR, which reduced cyst growth in autosomal-recessive PKD (ARPKD) mice, was recently tested for efficacy and safety in a clinical phase-2 study in ADPKD patients (ClinicalTrials.gov Identifier: NCT03203642)." (PMID 34650051, 2021).
epilepsy (3 papers, 2019 to 2022). A brain disorder characterized by episodes of abnormally increased neuronal discharge resulting in transient episodes of sensory or motor neurological dysfunction, or psychic dysfunction. "Moreover, previous studies have shown that c-SRC is closely associated with epilepsy." (PMID 36034878, 2022). "In this study, the non-receptor tyrosine protein (SRC), which is involved in the essential functions of neurons, including proliferation and apoptosis, was predicted to be the target of aloesone associated with epilepsy by network pharmacology and molecular docking." (PMID 36034878, 2022).
Ewing sarcoma (3 papers, 2017 to 2022). A small round cell tumor that lacks morphologic, immunohistochemical, and electron microscopic evidence of neuroectodermal differentiation. "In Ewing sarcoma, IGF-1R binds to IGF to initiate SRC, MAPK, FAK, and other signaling pathways to synergistically stimulate the proliferation, survival, and migration of cancer cells in Ewing sarcoma." (PMID 35680570, 2022). "However in contrast to Ewing sarcoma cell lines, RTK activations were here abrogated by plerixafor, pertussis toxin, and SRC inhibitors, indicating RTKs as downstream elements rather than compensatory signals." (PMID 29776413, 2018).
Hyperglycemia (3 papers, 2021 to 2025). An increased concentration of glucose in the blood. "SRC is required for glucose utilization under hyperglycemia and mediates glucokinase activity, as well as its subcellular localization." (PMID 41011980, 2025).
Infertility (3 papers, 2019 to 2025). "Because decidualization is critical for pregnancy, its impairment may contribute to subfertility or infertility observed in SRC KO mice." (PMID 41128555, 2025). "Specifically, triple knockouts of SRC, YES, and FYN result in embryonic lethality, double knockouts of SRC and YES, or SRC and FYN, result in perinatal lethality, and a single knockout of SRC causes postnatal lethality or infertility, but a single knockout of YES or FYN is viable and fertile." (PMID 36016954, 2022). "Mechanistically, we show that i19VEGFR-1 has a strong ability to phosphorylate and activate SRC proto-oncogene non-receptor tyrosine kinases and a significant bias toward a decrease in expression in patients considered infertile by WHO criteria." (PMID 31645906, 2019).
invasive carcinoma (3 papers, 2006 to 2015). A carcinoma that is not confined to the epithelium, and has spread to the surrounding stroma. "Tumor progression to invasive carcinoma is associated with activation of SRC family kinase (SRC, YES, FYN) activity and loss of cellular cohesion." (PMID 26549256, 2015).
ischemic stroke (3 papers, 2020 to 2025). A stroke disorder caused by obstruction of blood flow to the brain, due to thrombotic (local blood clot formation) or embolic (due to a blood clot or other material traveling from another site) event. "All four biomarkers (SRC, TLR8, FCAR, and HIF1A) were significantly upregulated in ischemic stroke patients compared to healthy controls." (PMID 40948644, 2025).
lymph node metastasis (3 papers, 2019 to 2023). "Positive SRC expression was significantly associated with the presence of lymph node metastasis (p = 0.020), and advanced disease stage (p = 0.048)." (PMID 31731442, 2019). "Active SRC expression was found to significantly associate with advanced disease stages, presence of lymph node metastasis, and tumor recurrences in patients with laryngeal tumors, but not in the pharyngeal subgroup." (PMID 31731442, 2019). "The expression of FGFR4 or SRC positively correlated with higher AJCC stages, lymph node metastasis, and distant metastasis." (PMID 36923538, 2023). "Positive SRC expression was more frequent in bigger tumor sizes (T3, T4) and cases with lymph node metastasis (N+) in both locations, although the differences were not statistically significant." (PMID 31731442, 2019).
mesothelioma (3 papers, 2016 to 2023). A usually malignant and aggressive neoplasm of the mesothelium which is often associated with exposure to asbestos. "Similarly, we found that in all of the investigated eight mesothelioma cell lines SRC was strongly expressed and activated to a varying extent." (PMID 35392170, 2022). "Finally, we prioritised compounds to be tested in vivo using AI-based network propagation and show that single-agent SRC inhibition with saracatinib extend survival of our mesothelioma genetically-engineered mouse model well beyond the cisplatin/pemetrexed combination." (PMID 37938546, 2023). "Similarly, in other studies SRC inhibitors could induce cell death and cell cycle arrest in a subset of mesothelioma cell lines." (PMID 35392170, 2022). "In order to investigate if it has a similar effect in mesothelioma cells we treated eight MPM cell lines with nintedanib and analyzed the activation of SRC (assessed by the phosphorylation of Y416)." (PMID 35392170, 2022). "Src family kinase (SFK) is a group of nine non-receptor tyrosine kinases, including, beyond SRC, three members (Yes, Fyn, and Lyn) previously identified as pivotal players in mesothelioma." (PMID 27391433, 2016).
myocardial infarction (3 papers, 2022 to 2025). Gross necrosis of the myocardium, as a result of interruption of the blood supply to the area, as in coronary thrombosis. "Blockage of SRC can stabilize Flk/cadherin complexing, reduce edema as well as tissue damage after myocardial infarction." (PMID 36248430, 2022). "Additionally, SRC suppression reverses Cx43 remodeling and improves heart function following myocardial infarction." (PMID 36248430, 2022).
Nephropathy (3 papers, 2011 to 2025). A nonspecific term referring to disease or damage of the kidneys. "In the context of kidney disease, SRC activation has been linked to pro-inflammatory and pro-fibrotic responses." (PMID 40800999, 2025). "Meanwhile, B7-1 and phosphor-SRC levels were increased in the kidney from WT mice with LPS nephropathy." (PMID 29862277, 2018). "The HIV-1 Nef gene was found to selectively activate certain members of the SRC kinase family, including SRC itself, which may contribute to HIV-1-associated nephropathy which is the most common cause of chronic renal failure in HIV-1-infected individuals." (PMID 21811574, 2011).
Pleural effusion (3 papers, 2022 to 2025). The presence of an excessive amount of fluid in the pleural cavity. "Dasatinib, as a dual inhibitor of ABL and SRC kinases, has a lower specificity for the shape and charge of the binding sites, which makes it more likely to induce pleural effusion with lymphocytic infiltration." (PMID 40166069, 2025). "For comparison with other body fluids (i.e., plasma/serum, BAL, and pleural effusion), 153 out of 912 MV proteins were pleural effusion-specific proteins, including ABI1, BSG, CAV1, GRB2, RAS proteins, and SRC." (PMID 35158999, 2022). "Other proteins such as tetraspanins, RAS proteins (e.g., NRAS and RRAS), MHC proteins, complement component proteins, Src family kinases (e.g., SRC, LYN, HCK, and FGR), S100 calcium-binding proteins, and 14-3-3 proteins were found in the pleural effusion-derived MVs." (PMID 35158999, 2022).
schizophrenia (3 papers, 2019 to 2022). A major psychotic disorder characterized by abnormalities in the perception or expression of reality. "TRAF6, PRKACA and ACTN1 are all connected to both SRC and PSEN1 and therefore it might be useful to further investigate their interactions in order to better understand the mechanisms that could be involved in Schizophrenia." (PMID 32735660, 2020).
ulcerative colitis (3 papers, 2022 to 2025). An inflammatory bowel disease involving the mucosal surface of the large intestine and rectum. "Previous studies have detected abnormal SRC expression in cells of diseased intestinal tissue in various conditions, including ulcerative colitis (UC) and bowel cancer." (PMID 40559953, 2025). "The molecular docking analysis revealed promising binding affinities of ten BRLE bioactive compounds against four key ulcerative colitis-related targets (EGFR, SRC, STAT3, and AKT1), with binding scores ranging from −6.5 to −9.1 kcal/mol." (PMID 41465478, 2025). "Molecular docking studies were performed to evaluate the binding affinity and interaction profiles of ten bioactive compounds from BRLE against the four key protein targets (EGFR, SRC, STAT3, and AKT1) identified through network pharmacology analysis for ulcerative colitis treatment." (PMID 41465478, 2025). "SRC, EGFR, AKT1, and PIK3R1 were the targets of highest potential, and the PI3K/Akt and MAPK pathways may be essential for the treatment of ulcerative colitis by bisdemethoxycurcumin." (PMID 36615264, 2022). "Lucidenic acid A emerged as the most promising compound, demonstrating exceptional binding to SRC (−9.1 kcal/mol), EGFR (−8.3 kcal/mol), and AKT1 (−8.8 kcal/mol), suggesting a multi-target therapeutic approach advantageous for treating the complex pathophysiology of ulcerative colitis." (PMID 41465478, 2025).
viral infection (3 papers, 2022 to 2025). "SRC was associated with a viral infection and tumors and played a role in activating the protein tyrosine kinase (PTK) family." (PMID 41476996, 2025). "Endogenous coimmunoprecipitation experiments indicated that viral infection induced association of IRF3 with SRC, and P4 treatment further enhanced their association." (PMID 35468896, 2022). "Third, phosphorylation of IRF3Y107 by SRC was important for IRF3 association with TBK1 and its self-association, as well as induction of IFN-β upon viral infection." (PMID 35468896, 2022). "Firstly, either PGR- or SRC-deficiency impaired progesterone-triggered potentiation of IRF3 activation and antiviral gene expression following viral infection." (PMID 35468896, 2022).
Arrhythmia (2 papers, 2023 to 2025). Any cardiac rhythm other than the normal sinus rhythm. "SRC was proved to be activated in MI models, on the other hand, the inhibitors of SRC reduced the occurrence arrhythmias and sudden cardiac death in mice with a cardiac-specific activated renin-angiotensin system." (PMID 39936089, 2025).
Ataxia (2 papers, 2020 to 2022). Ataxia refers to impaired coordination of voluntary muscle movement. "Inhibition of SRC corrects Purkinje neurons’ basal firing and delays ataxia progression." (PMID 35892334, 2022).
B-cell lymphoma (2 papers, 2015 to 2023). "Chk1 inhibitors have been shown to be effective against mouse models Myc-driven malignancies, such as B-cell lymphoma, and Wee1 inhibitors enhance the efficacy of the SRC inhibitors in Burkitt lymphomas." (PMID 25428911, 2015).
carcinoids (2 papers, 2017). "There were fewer CNAs in carcinoids than in carcinomas; however ACs showed a hybrid pattern, whereby gains of TERT, SDHA, RICTOR, PIK3CA, MYCL and SRC were found at rates similar to those in carcinomas, whereas the MEN1 loss rate mirrored that of TCs." (PMID 27873319, 2017).
Cerebral ischemia (2 papers, 2018 to 2024). Restriction of arterial blood supply to the brain associated with insufficient oxygenation to support the metabolic requirements of the tissue. "Further network pharmacology and molecular docking analyses indicate that TB-2 possesses a potential therapeutic effect against cerebral ischemia, and its possible targets were SRC, MAPK1 and KDR." (PMID 39376614, 2024). "Molecular docking analysis revealed lower binding energies of TB-2 with SRC, MAPK1, and KDR, and the significant role of these targets in cerebral ischemia treatment has been documented in previous literature." (PMID 39376614, 2024). "The core intersecting targets between cerebral ischemia and TB-2 are EGFR, SRC, GSK3B, MAPK1, and KDR, which may serve as potential therapeutic targets." (PMID 39376614, 2024).
cryptosporidiosis (2 papers, 2022 to 2024). Intestinal infection with organisms of the genus Cryptosporidium. "First, we performed a target database search to obtain a total of 47 intersecting targets of oxymatrine for the treatment of cryptosporidiosis, including the core targets of ALB, IL-6, TNF, AKT1, CASP3, and SRC." (PMID 38914662, 2024).
hepatitis B (2 papers, 2024).
influenza (2 papers, 2025 to 2026). An acute viral infection of the respiratory tract, occurring in isolated cases, in epidemics, or in pandemics; it is caused by serologically different strains of viruses (influenzaviruses) designated A, B, and C, has a 3-day incubation period, and usually lasts for 3 to 10 days. "Network pharmacology identified genistein and daidzein as key bioactive constituents targeting hub proteins TNF, AKT1, EGFR, SRC, and MMP9, which mediate pathological process in influenza." (PMID 41957261, 2026).
intestinal tumor (2 papers, 2015 to 2019). "The fact that RASSF1A cooperates with APC loss to promote intestinal tumors suggests that SRC activation may contribute to colorectal tumorigenesis by promoting the tyrosine phosphorylations of both β-catenin and YAP1 that are required for nuclear localization and transcriptional activation." (PMID 26549256, 2015).
invasive breast carcinoma (2 papers, 2006 to 2010). A carcinoma that infiltrates the breast parenchyma. "In the RT–PCR cohort, LCK mRNA expression in invasive breast cancer was 14-fold less than SRC and was associated with improved disease-specific survival in the IHC cohort." (PMID 20717116, 2010). "As observed within the invasive breast cancer specimen, SRC and LYN were the highest-expressed SFK members in non-malignant breast tissue." (PMID 20717116, 2010). "As with the invasive breast cancer specimens, all other SFK members correlated with SRC expression." (PMID 20717116, 2010).
laryngeal tumors (2 papers, 2019 to 2024). "Thus, aberrant SRC expression/activation was found to significantly associate with advanced disease stages, presence of lymph node metastasis, and tumor recurrences in patients with laryngeal tumors, but not in the pharyngeal subgroup." (PMID 31731442, 2019). "Active SRC specifically emerged as an independent predictor of cancer-specific mortality in patients with laryngeal tumors, but not in the pharyngeal subgroup." (PMID 31731442, 2019).
liposarcoma (2 papers, 2018 to 2019). A usually painless malignant tumor that arises from adipose tissue. "For example, CDK4 is amplified in patients with well-differentiated liposarcoma and de-differentiated liposarcoma, hepatocyte growth factor receptor (MET) is overexpressed in de-differentiated liposarcoma, and SRC is activated in myxoid liposarcoma and pleomorphic liposarcoma." (PMID 29568347, 2018).
male infertility (2 papers, 2022 to 2023). The inability of the male to effect fertilization of an ovum after a specified period of unprotected intercourse. "For cases of unexplained male infertility or testicular inflammation, exploring BTB damage and the expression of sICAM-1, SRC, and related signals could illuminate underlying causes." (PMID 38260159, 2023). "A more in-depth understanding of the sICAM-1/SRC signaling mechanisms promises to yield valuable insights for manipulating BTB permeability and addressing male infertility." (PMID 38260159, 2023). "This knowledge could enable strategies targeting sICAM-1/SRC to modulate BTB permeability and treat male infertility or diseases involving endothelial/epithelial barrier dysfunction." (PMID 38260159, 2023).
metastatic melanoma (2 papers, 2010 to 2012). A melanoma that has spread from its primary site to another anatomic site. "Therefore, the expression pattern of human NDRG2, VDR, NSD1, CTCF and SRC genes in several human metastatic melanoma cell lines in comparison to primary melanocytes were analyzed at mRNA level by RT-qPCR methodology." (PMID 22984562, 2012).
myeloid leukemia (2 papers, 2022 to 2026). A clonal proliferation of myeloid cells and their precursors in the bone marrow, peripheral blood, and spleen. "SRC inhibitor dasatinib is already approved for patients with specific myeloid leukemias, and it is in clinical studies for other indications." (PMID 36051080, 2022).
pancreatitis (2 papers, 2018 to 2025). Inflammation of the pancreas. "Activation of SRC mediate cofilin activation, which is important in the regulation of insulin secretin and pancreatic acinar depolymerization/reorganization related with pathogenesis of pancreatitis." (PMID 40308779, 2025).
Parkinson’s (2 papers, 2017 to 2023). "c-SRC and other tyrosine-phosphorylating protein kinases with a similar structure to c-SRC gave rise to the concept of Src family kinases (SFKs), SFK stimulation has been associated with microglial activation and neuropathological conditions, including Alzheimer’s and Parkinson’s." (PMID 37187578, 2023).
small cell lung carcinoma (2 papers, 2017 to 2021). Small cell lung cancer (SCLC) is a highly aggressive malignant neoplasm, accounting for 10-15% of lung cancer cases, characterized byrapid growth, and early metastasis. "Previous studies have shown synergistic effects using combinations of SRC and AKT inhibitors in small cell lung cancers." (PMID 28118365, 2017).
stomach adenocarcinoma (2 papers, 2024 to 2025). "Subtype-specific investigations revealed that SRC and PINK1 expression varied significantly among subtypes 1–4 in KIRC, stomach adenocarcinoma (STAD) and BRCA molecular subtypes (Basal, Her2, LumA, LumB, normal-like)." (PMID 39859167, 2025).
systemic sclerosis (2 papers, 2015 to 2017). A chronic disorder, possibly autoimmune, marked by excessive production of collagen which results in hardening and thickening of body tissues. "Here, the authors show that PTP4A1 is highly expressed by fibroblasts from patients with systemic sclerosis and promotes TGFβ activity via SRC–ERK–SMAD3 signaling." (PMID 29057934, 2017).
testicular cancer (2 papers, 2009 to 2021). A primary or metastatic malignant neoplasm that affects the testis. "SRC is a commonly known proto-oncogene, the somatic mutations of which promote the development, progression and metastasis of various malignancies including colorectal, breast, prostate, ovarian, and testicular cancers." (PMID 33916261, 2021). "GFAP is known to interact with the oncogenic tyrosine kinase SRC and involved in astrocyte tumor invasiveness, while TSP50 has been shown to be differentially regulated in both breast and testicular cancer." (PMID 19180177, 2009).